ADAMTS5 (ADAM metallopeptidase with thrombospondin type 1 motif 5)
Description:
Metalloproteinase that plays an important role in connective tissue organization, development, inflammation and cell migration. Extracellular matrix (ECM) degrading enzyme that show proteolytic activity toward the hyalectan group of chondroitin sulfate proteoglycans (CSPGs) including ACAN, VCAN, BCAN and NCAN. Cleavage within the hyalectans occurs at Glu-Xaa recognition motifs. Plays a role in embryonic development, including limb and cardiac morphogenesis, and skeletal muscle development through its VCAN remodeling properties. Cleaves VCAN in the pericellular matrix surrounding myoblasts, facilitating myoblast contact and fusion which is required for skeletal muscle development and regeneration (By similarity). Participates in development of brown adipose tissue and browning of white adipose tissue (By similarity). Plays an important role for T-lymphocyte migration from draining lymph nodes following viral infection.
Synonyms: ADAM-TS 5; ADAM-TS5; ADAMTS-5; ADAM-TS 11; ADAMTS-11; ADAMTS11; ADMP-2
Tractability: Small molecule: a drug acting on it is in phase 2 or 3 trials; a structure with a bound ligand is known; a high-quality ligand is known; it has a binding pocket of medium quality; it belongs to a druggable protein family. Antibody: UniProt places it where antibodies can reach, with high confidence; its Gene Ontology location is reachable by antibodies, with high confidence; UniProt predicts a signal peptide or a membrane-spanning region. PROTAC: ubiquitination databases record sites on it; a small molecule that binds it is known.
Target class: Metallo protease MAM clan; Metallo protease; Protease; Enzyme; Metallo protease M12B subfamily
Chemical probes: CHEMBL2164094
Gene: Protein-coding gene on chromosome 21 (26,917,922 to 26,967,088, reverse strand). Ensembl gene ENSG00000154736.
Subcellular location: Secreted, extracellular space, extracellular matrix
Pathways (Reactome):
Disease: Defective B3GALTL causes PpS
Extracellular matrix organization: Degradation of the extracellular matrix
Metabolism of proteins: O-glycosylation of TSR domain-containing proteins
Gene Ontology:
Molecular function: identical protein binding; metalloendopeptidase activity; metallopeptidase activity; peptidase activity; protein binding; endopeptidase activity; integrin binding; extracellular matrix binding; heparin binding; zinc ion binding
Biological process: aortic valve morphogenesis; endocardial cushion morphogenesis; extracellular matrix disassembly; extracellular matrix organization; myoblast fusion; negative regulation of cold-induced thermogenesis; proteolysis; pulmonary valve morphogenesis
Cellular component: endoplasmic reticulum lumen; extracellular matrix; extracellular region
Genetic constraint (gnomAD): Loss-of-function variants: 54 observed, 82.83 expected, observed/expected ratio (o/e) 0.65, 90% interval 0.52 to 0.82. The upper end of that interval is the gene's LOEUF score, 0.82, which puts it in group 3 of 6, group 1 being the genes least tolerant of losing a copy. Missense variants: 1,194 observed, 1,258.3 expected, observed/expected ratio (o/e) 0.95, 90% interval 0.9 to 1. Synonymous variants: 532 observed, 521.01 expected, observed/expected ratio (o/e) 1.02, 90% interval 0.95 to 1.1.
Homologues: Orthologues: chimpanzee ADAMTS5 (99% identical), macaque ADAMTS5 (98% identical), pig ADAMTS5 (93% identical), rabbit ADAMTS5 (93% identical), dog ADAMTS5 (92% identical), rat Adamts5 (91% identical), mouse Adamts5 (90% identical), guinea pig ADAMTS5 (88% identical), tropical clawed frog adamts5 (72% identical), zebrafish adamts5 (63% identical). Paralogues in human: ADAMTS15 (41% identical), ADAMTS1 (40% identical), ADAMTS8 (37% identical), ADAMTS9 (36% identical), ADAMTS20 (35% identical), ADAMTS4 (34% identical), ADAMTS7 (31% identical), ADAMTS6 (30% identical), ADAMTS18 (29% identical), ADAMTS10 (28% identical), ADAMTS3 (28% identical), ADAMTS16 (28% identical), and 13 more.
Diseases named in the same sentence as ADAMTS5 in open-access papers:
ADAMTS5 is named in the same sentence as 118 diseases in open-access papers, as found by Europe PMC text mining. Sharing a sentence is not in itself a finding about the gene and the disease. The quoted sentences say what the papers report.
osteoarthritis (102 papers, 2005 to 2026). A noninflammatory degenerative joint disease occurring chiefly in older persons, characterized by degeneration of the articular cartilage, hypertrophy of bone at the margins and changes in the synovial membrane. "For instance, ADAMTS5, a metalloprotease previously linked to osteoarthritis, emerged as a neuroprotective factor." (PMID 40355913, 2025). "ADAMTS13 is associated with thrombotic thrombocytopenic purpura, ADAMTS5 with osteoarthritis, and ADAMTS7 is associated with atherosclerosis and coronary artery disease." (PMID 39329961, 2024). "In particular, ADAMTS5 (aggrecanase-2) overexpression is a key risk factor in degenerative joint diseases and intervertebral disc degeneration." (PMID 34434966, 2021). "Many studies indicate that genetics is an important risk factor for osteoarthritis, and a disintegrin and metalloproteinase with thrombospondin motifs 5 (ADAMTS5) is one gene that is most frequently implicated." (PMID 34946864, 2021). "Dysregulated aggrecanase activity of ADAMTS-5 has been directly linked to the etiology of osteoarthritis (OA)." (PMID 33441904, 2021). "Conversely, ADAMTS-5 is closely associated with a heightened inflammatory state (best described in the context of osteoarthritis)." (PMID 32156081, 2020). "Osteoarthritis (OA) is associated with cartilage breakdown, brought about by ADAMTS-5 mediated aggrecan degradation followed by MMP-derived aggrecan and type II collagen degradation." (PMID 32825512, 2020). "ADAMTS-4 and ADAMTS-5 are proteases with important developmental roles, associated with inflammatory disorders, in particular osteoarthritis, where cartilage degradation results in joint pain." (PMID 33063247, 2020). "We have recently demonstrated that Ucma inhibits ADAMTS4 and ADAMTS5 aggrecanase activity in vitro and that Ucma-deficient mice develop a more severe cartilage damage in experimental osteoarthritis." (PMID 29720262, 2018). "High expression of this gene is strongly associated with osteoarthritis and mice that are homozygous for a catalytically inactive ADAMTS5 are protected against osteoarthritis when challenged with physical or chemical joint injury." (PMID 18478108, 2008). "Adamts5 encodes for a member of a disintegrin and metalloproteinase protein family with thrombospondin motifs, which may be involved in osteoarthritis." (PMID 34142176, 2022). "We used a meta-analysis and trial sequential analysis to determine whether ADAMTS5 rs226794 expression increases susceptibility to osteoarthritis." (PMID 34946864, 2021). "The cleaving process mediated by ADAMTS-4 and ADAMTS-5 releases the chondroitin sulfate–modified C-terminus from the chondrocytes into the synovium, and inhibitors could prevent osteoarthritis cartilage loss." (PMID 33063247, 2020). "Alteration of the osteoarthritis pathway due to RARγ agonist treatment was associated with the up-regulation of catabolic genes (ADAMTS5, HES1, and MMP13), inhibition of cartilage matrix anabolic genes (COL2A1, ACAN, and SOX9) and the up-regulation of death genes (CASP4)." (PMID 32294904, 2020). "Guava leaf extract and ellagic acid, one of its polyphenolic components, inhibit the activity of a disintegrin and metalloproteinase with thrombospondin type 5 (ADAMTS‐5), which is associated with aggrecan degeneration during the early stage of osteoarthritis (OA)." (PMID 29983942, 2018). "Due to its role in removing aggrecan in the progression of osteoarthritis (OA), ADAMTS-5 is often regarded as a potential therapeutic target for OA." (PMID 40362332, 2025). "Nevertheless, our data can be used to design small molecule inhibitors for other pharmaceutical targets, for example ADAMTS4 and ADAMTS5 in osteoarthritis, ADAMTS7 in atherosclerosis, or ADAMTS8 in pulmonary arterial hypertension, which spare ADAMTS9." (PMID 40449594, 2025). "ADAMTS5 has been extensively studied in osteoarthritis, where its catalytic activity has been shown to contribute to the disease progression." (PMID 40164572, 2025).
osteoarthritis (continued). "To explore the specific molecular mechanisms by which chronic circadian rhythm disruption causes osteoarthritis lesions in rat mandibular condylar cartilage, we examined the expression of matrix-degrading enzymes MMP13, ADAMTS4, and ADAMTS5." (PMID 39010104, 2024). "To test a combined role for ADAMTS1 and ADAMTS5, we undertook pharmacological ADAMTS5 inactivation in Adamts1 null embryos using a function-blocking antibody which was originally generated to target ADAMTS5 in osteoarthritis." (PMID 38750698, 2024). "Increased expression of β-CATENIN has been found to directly increase the expression of MMP13, ADAMTS4, and ADAMTS5, ultimately leading to the degradation of joint cartilage matrix and the occurrence of osteoarthritis lesions." (PMID 39010104, 2024). "In osteoarthritis (OA), articular homeostasis is regulated by microRNA-140 that inhibits ADAMTS-5, an enzyme that cleaves aggrecan and stimulates the synthesis of other inflammatory mediators." (PMID 39170063, 2024). "Studies have shown that injecting small interfering RNA (siRNA) with ADAMTS-5 through intra-articular injection can effectively delay the progression of osteoarthritis in mice." (PMID 36803799, 2023). "Liu and coworkers observed that MALAT1 sponged miR-145 and elevated ADAMTS5, resulting in regulation of IL-β-mediated viability and cartilage matrix degradation in osteoarthritis." (PMID 37779916, 2023). "In previous studies, ADAMTS5 has always been recognized as a symbolling molecule of osteoarthritis, and the positive results in MR analysis suggested its potential role in osteoporosis, which updated the current understanding on this metalloproteinase." (PMID 37468870, 2023). "ADAMTS5 is an aggrecanase that cleaves aggrecan, a major proteoglycan of cartilage, and mediate cartilage destruction in osteoarthritis." (PMID 36805735, 2023). "Embryonic stem cells can enhance the expression level of Col II in the cartilage matrix and reduce the expression of ADAMTS5, providing a new target for the development of osteoarthritis drugs and drug delivery systems." (PMID 36678850, 2023). "For example, Sal B dose-dependently suppressed IL-β induced the expression of iNOS, COX-2, MMP-13 and ADAMTS-5 via the inhibition of NF-κB p65 signaling in human osteoarthritis chondrocytes." (PMID 35922815, 2022). "The inhibitory effect of Mg2+ on IL-1β, MMP13, and ADAMTS5 indicates that it has a certain potential in the treatment of osteoarthritis and 5–7.5 mM Mg2+ was most effective in inhibiting cartilage catabolism." (PMID 36546928, 2022). "Members of the ADAMTS (a disintegrin and metalloproteinase with thrombospondin motifs) family, mainly ADAMTS-4 and ADAMTS-5, are major aggrecan-degrading enzymes in osteoarthritis." (PMID 36362216, 2022). "GLPG1972/S201086 is a disintegrin and metalloproteinase with thrombospondin motif‐5 (ADAMTS‐5) inhibitor in development as an osteoarthritis disease‐modifying therapy." (PMID 34859612, 2022). "ADAMTS-5 has been reported to have the highest activity in this family to accelerate the development of osteoarthritis." (PMID 34164391, 2021). "As a result, using a syndecan-4-specific antibody inhibits the activation of ADAMTS-5, thereby slowing the progression of osteoarthritis." (PMID 34868573, 2021). "For the meta-analysis, databases such as PubMed, Embase, and Cochrane were queried to identify studies that examined the relationship between ADAMTS5 rs226794 and osteoarthritis." (PMID 34946864, 2021). "From a pharmaceutical perspective, ADAMTS-5 is therefore a promising therapeutic target for the treatment of degenerative joint diseases such as OA." (PMID 33441904, 2021). "Specific binding between p65 and NF-κB binding motifs in the ADAMTS5 promoter suggested a transcriptionally induction of ADAMTS5 expression during osteoarthritis development." (PMID 34434966, 2021).
osteoarthritis (continued). "As a consequence, any treatment for osteoarthritis should aim to spare ADAMTS-5 activity in the blood vessels to avoid imbalance in PG levels." (PMID 33352066, 2020). "ADAMTS-5 is an important pharmacological target for osteoarthritis, where excess degradation of its substrate aggrecan leads to cartilage destruction." (PMID 32156081, 2020). "ADAMTS-5 has been extensively studied in the context of aggrecan degradation in cartilage and is a validated target for the treatment of osteoarthritis." (PMID 33352066, 2020). "A disinterring and metalloproteinase with thrombospondin motifs 4 and 5 (ADAMTS-4 and ADAMTS-5) have shown a critical role in cartilage destruction, and their expression is increased in osteoarthritis patients." (PMID 32349420, 2020). "ADAMTS-5 is a secreted protease that is involved in various pathophysiological processes, such as osteoarthritis, intervertebral disc degeneration, cancer, and angiogenesis." (PMID 32923459, 2020). "By the way, the degradation of articular cartilage in osteoarthritis is thought to be the results of ADAMTS5 and likely also of ADAMTS4 activity, two enzymes thought to be involved in degradation of certain SLRPs, e.g., of fibromodulin as well." (PMID 33028365, 2020). "This prominent microRNA can target osteoarthritis (OA)-related mRNAs, ADAMTS-5, MMP13, COl2a1, and ACAN in human articular chondrocytes." (PMID 31847882, 2019). "Conversely, the addition of NAPA decreased the chondrocyte expression of most of these genes at 24 hours: ADAMTS5, the pivotal matrix-degrading enzymes in osteoarthritis and IL-6 and MCP-1." (PMID 31537813, 2019). "ADAMTS5 appears to be the primary aggrecanase, which is responsible for aggrecanolysis and cartilage degeneration in murine experimental osteoarthritis, while evidence rises for a contribution of both ADAMTS5 and ADAMTS4 in human cartilage degradation." (PMID 29720262, 2018). "New therapies based on reducing or inhibiting the levels of ADAMTS-5 using an anti-ADAMTS-5 antibody in animal models of osteoarthritis have been reported." (PMID 29137610, 2017). "Inflammatory cytokines, including IL-1β and TNF-α, downregulate mir-140 expression leading to the development of osteoarthritis, most likely due to accelerated inflammation and/or ADAMTS5 activation." (PMID 28099924, 2017). "Other studies have shown that deletion of active ADAMTS5 prevents cartilage degradation in a murine model of osteoarthritis." (PMID 27562730, 2016). "Recently, three groups reported antibody-based exosite inhibitors of ADAMTS5, which were generated for therapeutic purposes to protect the destruction of articular cartilage in osteoarthritis." (PMID 27196928, 2016). "In the context of osteoarthritis, both the collagenase MMP-13 and the aggrecanases ADAMTS-4 and ADAMTS-5 are susceptible to such ECM-mediated increase in TIMP-3 potency." (PMID 27582494, 2016). "Remarkably, inhibition of Hh in explant cultures of human osteoarthritic cartilage samples blocked expression of key genetic markers of osteoarthritis, including the metalloproteinases ADAMTS5 and MMP13, the transcription factor RUNX2, and COL10A131." (PMID 25992955, 2015). "In additional studies in a murine model of osteoarthritis, deletion of ADAMTS-5 provided significant protection against proteoglycan degradation ex vivo and decreased the severity of osteoarthritis." (PMID 22513174, 2012). "Adamts5 is mostly studied in connection with osteoarthritis and in articular cartilage due to the observation that Adamts5−/− mice are protected from cartilage degradation in a model of osteoarthritis." (PMID 20111593, 2010). "In a murine model of osteoarthritis, ADAMTS5-knockout mice have a significantly reduced level of cartilage destruction, compared with wild-type mice." (PMID 19889209, 2009). "The discovery of the role of ADAMTS5 in osteoarthritis was a major step forward in understanding the pathology of this disease and presented an obvious target for drug development." (PMID 18478108, 2008).